MET (MET proto-oncogene, receptor tyrosine kinase)
Diseases named in the same sentence as MET in open-access papers (continued):
Sharing a sentence is not in itself a finding about the gene and the disease.
metastatic disease (56 papers, 2008 to 2025). "Our patient had bone lesions early in the course of his metastatic disease, which is in line with the c-MET hyperactivity seen in germline mutations of hereditary papillary RCC and bone metastases of RCC." (PMID 26654961, 2015). "Specific MET mutations are also known to control the progression of primary cancers to metastatic disease; a germline mutation of MET, MET-T1010I, was found in patients with metastatic breast cancer and is sufficient to induce tumor formation and invasion in-vivo." (PMID 40560045, 2025). "In addition, elevated c-MET expression and/or amplification has also been associated with depth of tumor (T) invasion, lymphovascular invasion, presence of regional lymph node and distant metastatic disease in CRC." (PMID 27793046, 2016). "In addition, as the re-expression of E-cadherin is proposed to be the important hallmark of MET, it also suggested that the MET might play an important role in metastatic tumor formation of HCC." (PMID 24059685, 2013). "In Case 1, after disease progression, the gene test results of the metastatic tumors revealed MET gene amplification." (PMID 41383499, 2025). "While MET exon 14 skipping transcripts have not previously been reported in primary UMs, there is emerging evidence of cMET protein overexpression in primary and metastatic UM, indicating a promising therapeutic target for patients with metastatic disease." (PMID 39766052, 2024). "In this context, our study supports the use of MET inhibitors to prevent and/or treat metastatic disease independently of dominant oncogenic signaling." (PMID 37345079, 2023). "In this study, they found 7% of patients with MET amplification in plasma, most of them with metastatic disease." (PMID 32102486, 2020). "Our data reveal that clear-cell RCC with MET upregulation show an aggressive behavior and MET copy number increase is evident in a substantial percentage of patients with high-grade carcinomas and metastatic disease." (PMID 27894094, 2017). "A higher than expected range of c-MET mutations noted in our review is perhaps in parallel with the notion of clustering of c-MET with metastatic fronds, as greater than 95% of cases in our study were of metastatic tumors." (PMID 26097886, 2015). "Since the HGF-MET axis is frequently dysregulated in many types of cancer and MET dysregulation is associated with an increased propensity for metastatic disease and poor overall prognosis, HGF/MET inhibition has emerged as a target for anticancer therapies." (PMID 25839163, 2015). "By contrast, the adenocarcinoma cell line H1993 from a metastatic tumor showed a very potent activation of the c-MET pathway, with also a high activation of the HER2 and SHC pathways, and a moderate activation of the HER3 and HER1 pathways." (PMID 22091388, 2011). "The majority of targeted compounds, for example, EGFR, BRAF and MET inhibitors, as well as molecules directed towards rearranged kinases, are particularly effective when administered in the very beginning of the treatment of metastatic disease." (PMID 38966170, 2024). "On the contrary, the median time to distant metastasis for those with negative MET expression was longer than that with mild expression, which is in line with the known role of MET in the development of metastatic disease at distant sites, as demonstrated in several malignancies." (PMID 37104404, 2023). "Moreover, the molecular landscape of OCCC revealed several potential therapeutical targets including MET fusion, and molecular testing can provide the potential for targeted therapy in patients with recurrent or metastatic tumors." (PMID 37303048, 2023). "For patients with metastatic disease, the outcome largely depends on the identification of a targetable driver such as EGFR, ALK, ROS1, ERBB2, BRAF, MET and more recently KRAS, RET, NRG1 and NTRK1-2-3, as mutations or gene fusions are highly predictive of response to matched targeted therapy." (PMID 35326552, 2022).
metastatic disease (continued). "However, only ErbB2 and MET levels were found to be statistically different between samples from primary and metastatic tumor tissue and, along with ErbB3, they exhibited the highest variation of expression values." (PMID 29719603, 2018). "Now, combining with what we have found in the clinical specimens, it could be speculated that in HCC, MET might also play an important role in metastatic tumor formation, and HNF4alpha might just be the important inducer of the MET, or act as an important part of the MET inducers." (PMID 24059685, 2013). "Accordingly, elevated expression of RPs and Eif4a1 was also detected in both prostate primary and metastatic tumor cells, aligning with upregulated XPO1, HGF/MET, and Wnt/β-catenin downstream target expression." (PMID 38336745, 2024). "Tepotinib is another nonselective c-MET inhibitor that is being investigated in a Phase II study (NCT04647838) in patients with solid cancers harboring c-MET amplification or exon 14 mutation who progressed after standard treatment for metastatic disease, including mCRC." (PMID 38269272, 2023). "With the increase in c-Met protein levels, there is also an increase in the number of MET copies in the primary and metastatic tumors." (PMID 30909397, 2019). "Primary or metastatic tumor samples from 99 patients with metastatic GE adenocarcinoma were tested with NGS and/or FISH for MET amplification." (PMID 26082439, 2015). "The cellsare derived from pleural effusion and models metastatic disease, withresearch suggesting that it harbors a c-met polymorphismthat is characteristic of papillary RCC.21 c-MET is a receptor tyrosine kinase which is key in cell differentiationand tissue repair in human tissue." (PMID 39398183, 2024). "In addition, cell lines that ectopically overexpress c-MET or HGF become transformed and metastasized in nude mice, and similarly, HGF or c-MET transgenic mice develop metastatic tumors." (PMID 28817103, 2017). "Therefore, in this study we aimed to experimentally examine whether HNF4alpha take part in the metastatic tumor formation of HCC and its relationship with the MET markers." (PMID 24059685, 2013).
head and neck cancer (49 papers, 2009 to 2025). A primary or metastatic malignant neoplasm affecting the head and neck. "Kumar and colleagues reported an autocrine loop triggered by HGF secreted by tumor-associated fibroblasts, which acts through MET to drive glycolysis in the progression of head and neck cancer." (PMID 38957115, 2024). "Studies have confirmed that c-MET activation is associated with adverse clinical outcomes in lung, breast, stomach, kidney, and head and neck cancers." (PMID 32295618, 2020). "On the other hand, MET mutation is causative for familial carcinomas, such as renal carcinoma or head-and-neck carcinoma in humans." (PMID 23296269, 2013). "This follow-up provides evidence for the potential of MET CN assessment when patients develop resistance to anti-EGFR therapy and a significant association between the presence of CTCs MET+ and the Overall Survival (OS) in head and neck cancer patients (P = 0.05; HR = 6.66)." (PMID 32102486, 2020). "This happens through genomic activation, like germline MET mutation, such as in hereditary papillary renal cell carcinoma or sporadic MET mutations, detected in various cancer types, including brain, gastric, and head and neck cancers or even protein over-expression." (PMID 30441809, 2018). "MET and/or PI3K pathway inhibition was assessed in NIH3T3 cells harboring MET-activating point mutation with or without ectopic expression of PIK3CAE545K and PIK3CAH1047R, as well as in MET-expressing head and neck cancer cells with endogenous PIK3CA mutations." (PMID 28532501, 2017). "In this study we have examined the impact of common PIK3CA helical and catalytic domains hotspot mutations upon MET inhibition in preclinical MET-driven and head and neck cancer models, providing therefore a first evaluation of MET targeting in the context of common PI3K mutations." (PMID 28532501, 2017). "Overexpression of HGF/MET is commonly observed in resistant head and neck cancer cells and this signaling helps the cells survive despite the detrimental effects of cetuximab." (PMID 40560045, 2025). "The link between HK2 expression and MET activation appears to be dependent on the cell line studied, as another group studying MET in head and neck cancer found that HGF treatment only induced HK2 and LDHA expression in one out of the three cell lines tested." (PMID 39062731, 2024). "We mined the TCGA’s head and neck cancer genomics data using the c-BioPortal website to study the roles of MET, STAT3, and AKT overexpression." (PMID 37373393, 2023). "In head and neck cancer, MET expression was significantly correlated with STAT3 (r = 0.269) and AKT (r = 0.503)." (PMID 37373393, 2023). "The TCGA head and neck cancer statistics were filtered, and it was discovered that MET, STAT3, and AKT gene expressions were greater than those in the control group." (PMID 37373393, 2023). "In head and neck cancer cells the combination of MET/PI3K inhibitors led to more-than-additive effects." (PMID 28532501, 2017). "Targeting MET, vascular endothelial growth factor receptor (VEGFR) and AXL using cabozantinib resulted in decreased migration, invasion, and proliferation causing apoptotic cell death in naïve and therapy resistant head and neck cancer cells." (PMID 38891113, 2024). "This review highlights the role of AXL, MET, and RON families of RTKs in tumor progression and resistance to anti-EGFR therapies, focusing on breast and head and neck cancers." (PMID 40560045, 2025). "The Oncomine database was utilized to analyze the expression of MET, STAT3, and AKT in head and neck cancer and normal tissue samples." (PMID 37373393, 2023). "MGCD265 is an oral, multi-targeted, receptor tyrosine kinase inhibitor that targets MET, AXL, and PDGFR and is in clinical trials for non-small cell lung cancer (NSCLC), head and neck cancers, and advanced malignancies." (PMID 27655711, 2016).
head and neck cancer (continued). "Our molecular docking studies suggest that promising selected compounds in head and neck cancer cells (HNSCC cells) could interact with human epidermal growth factor receptor 2 (HER2) and mesenchymal–epithelial transition factor (c-MET)." (PMID 40430804, 2025). "One study reported that c-MET expression in CTCs enriched by size-based filtration showed poorer OS in a small number of patients with head and neck cancers (n = 11) but not in patients with BC." (PMID 38238761, 2024). "The RTK MET, the high-affinity receptor for hepatocyte growth factor (HGF), functions as an oncogenic driver in many distinct human tumors, including gastric, lung, brain, and head and neck cancers." (PMID 38957115, 2024). "Similarly to EGFR, the MET RTK is a promising candidate for targeted therapy, notably for gastric, lung, and head and neck cancer, where MET overexpression or amplification can often be observed." (PMID 37188738, 2023). "In addition, the Human Protein Atlas database was utilized to confirm the histological levels of MET, STAT3, and AKT, and the results indicate that these genes were elevated in head and neck cancer tissue relative to normal tissue." (PMID 37373393, 2023). "Oncogenic MET-mutants are responsible for PRCs and head-and-neck carcinoma, but these are not common in many types of malignant tumors." (PMID 23296269, 2013).
lymph node metastasis (49 papers, 2011 to 2025). "We also found the positive expression of MET was associated with lymph node metastasis, pathological TNM, and pathological stage in TNBC patients significantly." (PMID 34123778, 2021). "Both markers are involved in tumor invasion and metastasis, and the overexpression of c-MET has been linked to lymph node metastasis and clinicopathological staging." (PMID 33142750, 2020). "High MET mRNA expression (score ≥3) was associated with lymph node metastasis (P = .014), distant metastasis (P = .001), and higher TNM stage (P<.001)." (PMID 25364819, 2014). "In assessment of lymph node metastasis and vascular invasion, there were a relative association (0.05 < P < 0.1) between c-MET expression and both of them." (PMID 22640970, 2012). "High c-MET expression is linked to an increased risk of lymph node metastasis in various tumours." (PMID 40078386, 2025). "MET-CD47 co-expression defined a novel independent prognosticator for overall-survival by multivariate analysis (Cox proportional hazards model: HR: 4.1, p<0.002) and CD47 expression alone or in combination with MET was strongly associated with lymph node metastasis." (PMID 25230070, 2014). "According to Spearman correlation analysis, the expression of ICAM1 was positively correlated with the expression of MET in the PTC lymph node metastasis group (r = 0.5736, P < 0.0001)." (PMID 37274228, 2023). "This difference in MET expression levels in time to lymph node metastasis versus that in distant metastasis was also noted when evaluating canine oral melanomas specifically." (PMID 37104404, 2023). "CAGE was more frequently expressed in patients with pADCs with lymph node metastasis and was positively correlated with the expression of c-MET." (PMID 37735252, 2023). "MET positive rate was 87.9% and although expression of MET protein was significant correlated with lymph node metastasis (p < 0.001), MET positive was higher in pN0 stage." (PMID 28052014, 2017). "They reported the positive rate of MET was 59.18% and expression of MET protein was significant correlated with lymph node metastasis (p = 0.041)." (PMID 28052014, 2017). "MET positivity was associated with larger tumor size (> 5 cm, P = 0.041), presence of lymphovascular invasion (LVI, P = 0.025), lymph node metastasis (LNM, P = 0.030), and MMR deficiency (P < 0.001)." (PMID 27765925, 2016). "Expression of MET has been shown to be correlated with lymph node metastasis, distant metastasis, and cancer patients’ prognosis." (PMID 25874496, 2015). "The expression level of c-MET mRNA was associated with lymph node metastasis, tumour grade and stage but not significantly with the gender of the patients." (PMID 40078386, 2025). "Here, MET was regulated in the SCLC patients with lymph node metastasis." (PMID 30364292, 2018). "In the high lymph-node metastasis (N2 and N3) group, SMAD2 expression was more frequent, as was ERBB2 and MET expression." (PMID 35650563, 2022). "Positive expression of MET and FASN were significantly correlated with lymph node metastasis, pathological TNM, and pathological Stage." (PMID 34123778, 2021). "Positive expression of MET and FASN were correlated with lymph node metastasis, pathological TNM, and pathological Stage." (PMID 34123778, 2021). "According to the IHC staining results, the lymph node metastasis group had a higher expression of MET and ICAM1 than the lymph node non-metastasis group." (PMID 37274228, 2023). "c-MET positive expression was also more often observed with patients in N1 lymph node metastasis than without nodal involvement (N0 subgroup)." (PMID 37240178, 2023). "CDK6, MET, NOTCH1, and LRP1B mutation frequencies showed significant differences in cases with (N ≥ 1) or without (N = 0) lymph node metastasis." (PMID 34152098, 2021). "Lymph node metastasis and pT3/T4 GC was more common in the c-MET-negative group, but without reached statistical significance." (PMID 35076580, 2021).
lymph node metastasis (continued). "These proteins have been reported to have a close correlation with lymph node metastasis as ERBB2 and c-Met were positive in 76% (19/25) and 16% (4/25) of metastatic lymph nodes in patients with ICC, and high c-MET expression was significantly correlated with poor survival of these patients." (PMID 32708604, 2020). "Our study also shows for the first time that co-expression of MET and CD47 in luminal-type primary tumors represents an even better independent predictor for reduced overall-survival compared to expression of MET or CD47 alone and that it strongly correlates with lymph node metastasis." (PMID 25230070, 2014). "However, a lymph node metastasis of this patient was shown to be highly amplified by both SRM and FISH, suggesting that the primary tumor harbored a subclonal population of MET amplified cells which seeded the lymph node metastasis." (PMID 24983965, 2014). "Specifically, the mutation frequencies of CDK6, MET, and NOTCH1 noticeably lower in cases with stage N0 than in those with stage N ≥ 1, whereas LRP1B mutation frequency was remarkably higher in cases without lymph node metastasis." (PMID 34152098, 2021). "To know the relationship of MET and FASN with the clinical pathological features, we carried out the correlation analysis and found that the positive expression of MET and FASN were significantly correlated with lymph node metastasis, pathological TNM, and pathological Stage." (PMID 34123778, 2021). "The Cancer Genome Atlas analysis revealed elevated c-MET expression in ESCA, which was significantly correlated with lymph node metastasis, tumour grade and stage, though not with overall survival (OS)." (PMID 40078386, 2025). "MET and ICAM1 had strong staining in the lymph node metastasis group and weak staining in the lymph node non-metastasis group." (PMID 37274228, 2023). "For validation at the experimental level, the expression of PTGS2, MET, and ICAM1 was analyzed via immunohistochemical staining of pathological sections from the lymph node metastasis and non-metastasis groups." (PMID 37274228, 2023). "Here, 186 upregulated (e.g., GSR, HCP5) and 144 downregulated DEGs (e.g., MET, GRM8, and DACH1) were identified between the SCLC patients with lymph node metastasis and without lymph node metastasis." (PMID 30364292, 2018). "However, IHC showed that the expression of MET and ICAM1 significantly differed between the lymph node metastasis and non-metastasis groups." (PMID 37274228, 2023).